RPS15A (ribosomal protein S15a)
Description:
Component of the small ribosomal subunit. Part of the small subunit (SSU) processome, first precursor of the small eukaryotic ribosomal subunit. During the assembly of the SSU processome in the nucleolus, many ribosome biogenesis factors, an RNA chaperone and ribosomal proteins associate with the nascent pre-rRNA and work in concert to generate RNA folding, modifications, rearrangements and cleavage as well as targeted degradation of pre-ribosomal RNA by the RNA exosome. Required for proper erythropoiesis.
Synonyms: S15A; uS8; DBA20
Tractability: Small molecule: an approved drug acts on it; a structure with a bound ligand is known; a high-quality ligand is known. PROTAC: ubiquitination databases record sites on it; its protein half-life has been measured; a small molecule that binds it is known. Other modalities: a drug acting on it is in phase 2 or 3 trials.
Target class: Other cytosolic protein
Gene: Protein-coding gene on chromosome 16 (18,781,295 to 18,790,383, reverse strand). Ensembl gene ENSG00000134419.
Subcellular location: Cytoplasm; Nucleus, nucleolus
Pathways (Reactome):
Metabolism of proteins: Eukaryotic Translation Termination; Formation of a pool of free 40S subunits; Formation of the ternary complex, and subsequently, the 43S complex; GTP hydrolysis and joining of the 60S ribosomal subunit; L13a-mediated translational silencing of Ceruloplasmin expression; PELO:HBS1L and ABCE1 dissociate a ribosome on a non-stop mRNA; Peptide chain elongation; Ribosomal scanning and start codon recognition; SRP-dependent cotranslational protein targeting to membrane; Translation initiation complex formation; ZNF598 and the Ribosome-associated Quality Trigger (RQT) complex dissociate a ribosome stalled on a no-go mRNA
Disease: SARS-CoV-1 modulates host translation machinery; SARS-CoV-2 modulates host translation machinery; Viral mRNA Translation
Metabolism of RNA: Major pathway of rRNA processing in the nucleolus and cytosol; Nonsense Mediated Decay (NMD) enhanced by the Exon Junction Complex (EJC); Nonsense Mediated Decay (NMD) independent of the Exon Junction Complex (EJC)
Cellular responses to stimuli: Response of EIF2AK4 (GCN2) to amino acid deficiency
Developmental Biology: Regulation of expression of SLITs and ROBOs
Metabolism: Selenocysteine synthesis
Gene Ontology:
Molecular function: protein binding; RNA binding; structural constituent of ribosome
Biological process: positive regulation of cell cycle; positive regulation of cell population proliferation; response to virus; ribosomal small subunit biogenesis; cytoplasmic translation; translation
Cellular component: cytoplasm; cytosolic ribosome; cytosolic small ribosomal subunit; extracellular exosome; membrane; small-subunit processome; cytosol; nucleoplasm; nucleolus; ribosome; synapse
Genetic constraint (gnomAD): Loss-of-function variants: 0 observed, 3.12 expected, observed/expected ratio (o/e) 0, 90% interval 0 to 0.95. That is too few expected variants to judge how well the gene tolerates losing a copy. Missense variants: 31 observed, 65.75 expected, observed/expected ratio (o/e) 0.47, 90% interval 0.35 to 0.64. Synonymous variants: 28 observed, 24.05 expected, observed/expected ratio (o/e) 1.16, 90% interval 0.86 to 1.59.
Homologues: Orthologues: chimpanzee RPS15A (100% identical), guinea pig RPS15A (100% identical), macaque RPS15A (100% identical), mouse Rps15a (100% identical), pig RPS15A (100% identical), tropical clawed frog rps15a (99% identical), zebrafish rps15a (99% identical), rat AABR07072261.1 (98% identical), Drosophila melanogaster RpS15Aa (88% identical), Drosophila melanogaster RpS15Ab (88% identical), Caenorhabditis elegans rps-22 (86% identical), rabbit RPS15A (78% identical).
Diseases named in the same sentence as RPS15A in open-access papers:
RPS15A is named in the same sentence as 42 diseases in open-access papers, as found by Europe PMC text mining. Sharing a sentence is not in itself a finding about the gene and the disease. The quoted sentences say what the papers report.
gastric cancer (9 papers, 2019 to 2024). A primary or metastatic malignant neoplasm involving the stomach. "Overexpression of RPS15A promoted the proliferation and migration of gastric cancer cells, which alleviated the inhibitory effect caused by PSMC2 knockdown to a certain extent." (PMID 35256584, 2022). "Torin1 restricted the proliferation ability of gastric cancer cells and induced apoptosis, and also restored the accelerated proliferation and the reduced apoptosis rate caused by overexpression of RPS15A." (PMID 35256584, 2022). "This study aimed to investigate the clinical significance, potential biological function and underlying mechanism of RPS15A in gastric cancer (GC) progression." (PMID 30661291, 2019). "Overexpression of RPS15A can activate the mTOR pathway and promote the proliferation of gastric cancer cells, thereby promoting the progression of gastric cancer." (PMID 39684863, 2024). "As a component of the 40S subunit, increased RPS15A expression is closely correlated with poor prognosis in gastric cancer (GC) patients and promotes epithelial-mesenchymal transition (EMT) and GC progression, as demonstrated." (PMID 37508365, 2023). "PSMC2 enhanced RPS15A levels by targeting hsa-let-7c-3p, and then activated mTOR pathway, thereby promoting the progression of gastric cancer." (PMID 35256584, 2022). "In summary, both PSMC2 and RPS15A were significantly overexpressed in gastric cancer, and PSMC2 upregulated RPS15A by inhibiting the expression of hsa-let-7c-3p." (PMID 35256584, 2022). "A recent study found that PSMC2 promotes gastric cancer progression by targeting hsa-let-7c-3p to increase the level of RPS15A, which then activates the mTOR pathway." (PMID 36110217, 2022). "In summary, PSMC2 activated mTOR pathway through upregulation of RPS15A, thus promoting the progression of gastric cancer." (PMID 35256584, 2022). "Knockdown of RPS15A decreased the proliferation and migration ability of gastric cancer cells, whereas overexpression of RPS15A alleviated the inhibition of PSMC2 knockdown on the proliferation and migration." (PMID 35256584, 2022). "We used TargetScan and TCGA databases to predict 7 downregulated miRNAs in gastric cancer that not only bound to PSMC2 but also targeted RPS15A." (PMID 35256584, 2022). "The mTOR pathway inhibitor Torin1 partially restored the promoting role of RPS15A overexpression on the gastric cancer cell proliferation." (PMID 35256584, 2022). "For example, RPS15A was found to promote the progression of gastric carcinoma by activating the Akt pathway, and RPL11 expression was identified as a potential biomarker for predicting 5-fluorouracil (5-FU) sensitivity." (PMID 35847905, 2022). "The tumor promotor function of MCM8 in gastric cancer is realized by binding with RPS15A." (PMID 38988047, 2024). "Consequently, PSMC2 promoted the proliferation and migration of gastric cancer cells by upregulating RPS15A." (PMID 35256584, 2022). "In conclusion, PSMC2 and RPS15A were highly expressed in gastric cancer." (PMID 35256584, 2022). "In this study, RPS15A was also significantly upregulated in gastric cancer." (PMID 35256584, 2022). "This revealed that overexpression of PSMC2 upregulated the expression of RPS15A in gastric cancer." (PMID 35256584, 2022). "Furthermore, RPS15A is involved in the regulation of a variety of cancers, including glioblastoma, gastric cancer, lung cancer, hepatocellular carcinoma and pancreatic cancer." (PMID 34838013, 2021). "Therefore, we further explored the effect of PSMC2/RPS15A/mTOR pathway on gastric cancer." (PMID 35256584, 2022). "Besides, IPA results showed an interaction between PSMC2 and RPS15A/mTOR pathway, suggesting that PSMC2 might be involved in the progression of gastric cancer through RPS15A/mTOR pathway." (PMID 35256584, 2022). "Gastric cancer cells (AGS and MGC-803 cells) with RPS15A overexpression or RPS15A overexpression and PSMC2 knockdown were constructed in vitro." (PMID 35256584, 2022).
gastric cancer (continued). "Through bioinformatic analysis of the sequencing results of PSMC2 knockdown gastric cancer cells, it was found that PSMC2 overexpression upregulated ribosomal protein S15A (RPS15A) at the transcription and translation levels." (PMID 35256584, 2022). "However, there are still some deficiencies in this study, that is, more clinical samples are needed to detect the expression of hsa-let-7c-3p in gastric cancer, and to verify the correlation between PSMC2, hsa-let-7c-3p and RPS15A." (PMID 35256584, 2022). "However, the role and mechanism of PSMC2 regulating mTOR pathway through RPS15A in gastric cancer was not reported." (PMID 35256584, 2022). "In addition, we also confirmed that the promoting effect of PSMC2/RPS15A on gastric cancer progression, suggesting that PSMC2/RPS15A may be potential targets for targeted therapy of gastric cancer." (PMID 35256584, 2022).
glioblastoma (7 papers, 2016 to 2024). The most malignant astrocytic tumor (WHO grade IV). "RPS15A was reported to be potentially involved in hepatocellular carcinoma, progression of breast cancer, lung adenocarcinoma, prostate cancer, glioblastoma, colorectal cancer, and acute myeloid leukemia as an oncogene." (PMID 36841815, 2023). "For example, RPS15A is highly expressed in human glioblastoma; RPS15A knockdown inhibits human glioblastoma progression in vitro and in vivo via the AKT pathway." (PMID 28922548, 2018). "To investigate the biological function of RPS15A in glioblastoma cells, we constructed two individual shRNA vectors for RPS15A knockdown using lentiviral vectors carrying green fluorescent protein (GFP)." (PMID 27130037, 2016). "RPS15A was found to be overexpressed in glioblastoma compared with normal tissue." (PMID 38729158, 2024). "RPS15A was reported to promote proliferation and migration via the Akt pathway in glioblastoma." (PMID 38729158, 2024). "A quick search of RPS15A gene in GBM revealed that this gene was up-regulated in several types of GBM, including anaplastic oligoastrocytoma, glioblastoma, oligodendroglioma, and diffuse astrocytoma vs. normal tissues." (PMID 27130037, 2016). "Here, we firstly conducted RPS15A gene expression analysis in brain cancer using Oncomine database and found RPS15A was remarkably overexpressed in glioblastoma (GBM) compared with that in normal tissues." (PMID 27130037, 2016). "For example, with glioblastoma, eS6 (RPS6), eS27 (RPS27), uS8 (RPS15A) and eL34 (RPL34) are known as oncogenic, whereas uL18 (RPL5), uS17 (RPS11), uS9 (RPS16) and uS13 (RPS18) are found to have a tumor-suppressive function." (PMID 37511213, 2023).
breast carcinoma (5 papers, 2021 to 2023). "RPS15A was upregulated in pancreatic cancer and breast cancer, and RPS15A knockdown inhibited cancer cell proliferation and induced apoptosis." (PMID 35256584, 2022). "In MDA-MB-231 cell lines, the knockdown of RPS15A suppresses breast cancer proliferation and induces apoptosis by increasing the caspase 3/7 activity, and suppressing the phosphorylated levels of ERK1/2, Bad and Chk1." (PMID 34873618, 2021). "A large amount of evidence demonstrated that RPS15A is abnormally highly expressed in various types of human cancers, including lung adenocarcinoma, hepatic cancer, colorectal cancer, breast cancer and osteosarcoma." (PMID 34838013, 2021). "The knockdown of RPS15A by shRNA in breast cancer cell line ZR-75-30 and BT474 mediates apoptosis via the activation of caspase-3 and PARP cleavage, the up-regulation of Bad and BAX and the down-regulation of Bcl-2 confirming the importance of RPS15 in the modulation of breast cancer development." (PMID 34873618, 2021).
pancreatic cancer (5 papers, 2021 to 2024). "Inhibition of RPS15A by miR-519d-3p leads to the down-regulation of Wnt/β-catenin pathway in pancreatic cancer which proves the potential role of RPS15A as a target to treat pancreatic cancer." (PMID 34873618, 2021). "Moreover, RPS15A exhibits high expression in pancreatic cancer cell lines and facilitates the proliferation of pancreatic cancer cells through the WNT/β-catenin pathway." (PMID 39684863, 2024). "In addition, RPS15A is highly expressed in pancreatic cancer cell lines and is inversely correlated with the tumor suppressor miR-519d-3p expression." (PMID 34873618, 2021).
hepatocellular carcinoma (4 papers, 2016 to 2024). A malignant tumor that arises from hepatocytes. "In hepatocellular carcinoma, RPS15A is upregulated, and high RPS15A expression predicts poor survival." (PMID 38388496, 2024). "Furthermore, it has been reported that downregulation of its mRNA expression in hepatocellular carcinoma cells significantly inhibits tumor growth, suggesting that RPS15A may play a role in human carcinogenesis." (PMID 26989627, 2016).
liver cancer (4 papers, 2021 to 2022). An epithelial or non-epithelial malignant neoplasm that arises from the liver. "Previous studies indicated that the overexpression of RPS15A in liver cancer was associated with poor overall survival and promoted the angiogenesis of liver cancer." (PMID 35256584, 2022). "In HCC cells HepG2, the knockdown of RPS15A by shRNA causes cell cycle arrest at G0/G1 phase suggesting that RPS15A could be a potential therapeutic target in liver cancer." (PMID 34873618, 2021).
lung adenocarcinoma (4 papers, 2016 to 2023). A carcinoma that arises from the lung and is characterized by the presence of malignant glandular epithelial cells. "We detected the expression of RPS15A protein in a tissue microarray (TMA) of primary lung adenocarcinoma and adjacent normal lung tissue specimens using immunohistochemical staining with an anti-RPS15A antibody." (PMID 26989627, 2016). "Correlation between RPS15A expression and clinicopathological factors in 75 lung adenocarcinoma patients specimens." (PMID 26989627, 2016). "In this regard, a lentivirus-mediated RNAi system was applied to inhibit RPS15A mRNA expression in human lung adenocarcinoma H1299 and A549 cells in vitro." (PMID 26989627, 2016). "RPS15A expression in 75 lung adenocarcinoma and adjacent normal tissue specimens." (PMID 26989627, 2016).
COVID-19 (3 papers, 2022 to 2024). A disease caused by infection with severe acute respiratory syndrome coronavirus 2. "Moreover, IFITM1 is down-regulated in the COVID-19 group (either mild or severe) compared with the healthy group, while RPS15A is down-regulated in the severe group compared with the healthy group." (PMID 35601483, 2022). "Also, spec_24h mRNAs were enriched in 12 KEGG terms such as Coronavirus disease-COVID-19, Ribosome, MAPK signaling pathway, Cytokine-cytokine receptor interaction, Focal adhesion, involving genes such as Rpl7, Rpl3, Rpl5, Rpl4, Rps15a." (PMID 38622534, 2024).
lung carcinoma (3 papers, 2016 to 2021). "To elucidate the downstream mechanisms underlying RPS15A silence in lung cancer, we carried out a human whole genome oligo microarray and KEGG pathway enrichment analysis." (PMID 26989627, 2016). "Similarly, down-regulation of RPS15A by siRNA is found to be linked with a decrease in lung cancer A549 cells proliferation through G0/G1 cell cycle arrest suggesting that these RPs could function as potential biomarkers in lung cancer." (PMID 34873618, 2021). "The present study was aimed to investigate whether RPS15A is involved in the development and progression of lung cancer." (PMID 26989627, 2016). "Therefore, the low colony-forming efficiency of Lv-shRPS15A infected H1299 and A549 cells demonstrated that RPS15A silencing inhibited the colony forming ability of lung cancer cells in vitro." (PMID 26989627, 2016). "This suggested that downregulation of RPS15A expression might trigger apoptosis in lung cancer cells, which contributed to the cell growth suppression." (PMID 26989627, 2016). "Furthermore, to further investigate the function of RPS15A in lung cancer, RPS15A-specific short hairpin RNA (shRNA) expressing lentivirus (Lv-shRPS15A) was constructed and used to infect H1299 and A549 cells." (PMID 26989627, 2016). "Therefore, our findings demonstrate that RPS15A is a novel oncogene in non-small cell lung cancer and may be a potential therapeutic target in lung cancer." (PMID 26989627, 2016). "Therefore, we hypothesized that RPS15A may play an important role in the proliferation of lung cancer." (PMID 26989627, 2016). "However, the role of RPS15A in lung cancer has not been completely studied." (PMID 26989627, 2016). "However, the role of RPS15A has not been fully revealed on the development of lung cancer." (PMID 26989627, 2016).